SSX7 (SSX family member 7)
Description:
Could act as a modulator of transcription.
Tractability: No criterion of Open Targets' tractability assessment is met for any kind of drug.
Gene: Protein-coding gene on chromosome X (52,644,061 to 52,654,900, reverse strand). Ensembl gene ENSG00000187754.
Subcellular location (Human Protein Atlas): Nucleoli; Nucleoplasm
Gene Ontology:
Molecular function: protein binding
Biological process: regulation of DNA-templated transcription
Cellular component: nucleus
Homologues: Orthologues: mouse Ssxb9 (32% identical), mouse Ssxb8 (32% identical), mouse Ssxb6 (31% identical), rat Ssx2 (31% identical), mouse Ssxb1 (31% identical), mouse Ssxb15 (31% identical), mouse Ssxb3 (31% identical), mouse Ssxb10 (30% identical), mouse Ssxb13 (30% identical), rat Ssx1 (30% identical), mouse Ssxb14 (30% identical), mouse Ssxb2 (29% identical), and 3 more. Paralogues in human: SSX2 (85% identical), SSX2B (85% identical), SSX3 (85% identical), SSX5 (83% identical), SSX4 (82% identical), SSX4B (82% identical), SSX1 (79% identical).